NOX4 (NADPH oxidase 4)
Diseases named in the same sentence as NOX4 in open-access papers (continued):
Sharing a sentence is not in itself a finding about the gene and the disease.
pulmonary fibrosis (continued). "In this regard, NOX4 is the only isoform of NOX proteins highly upregulated in the epithelial cells and myofibroblasts of lungs in idiopathic pulmonary fibrosis (IPF) patients." (PMID 33376577, 2020). "NOX4 plays a critical role in TGF-β-induced ROS production, fibroblast-to-myofibroblast differentiation, and pulmonary fibrosis." (PMID 31119153, 2019). "NOX4, a member of NADPH oxidases, plays an important role in the progression of organ fibrosis, such as liver fibrosis, pulmonary fibrosis, and scleroderma." (PMID 30993112, 2019). "Cumulative evidence indicated that NOX4-based NADPH oxidase is an important factor for oxidative stress induction and pathological alterations in liver and lung fibrosis as well as diabetic nephropathy." (PMID 26942460, 2016). "siRNA-meditated NOX4 knockdown and low-molecular-weight NOX4 antagonist have been shown to efficiently attenuate BLM-induced lung fibrosis, further supporting the notion that metformin-mediated NOX4 suppression can be a reasonable and promising IPF treatment." (PMID 27576730, 2016). "Several proteins, including NADPH oxidase 4, Toll-like receptor 3, CCL18, matrix metalloproteinase-7, and interleukin-8, besides TGF-β, are widely accepted as key players in pulmonary fibrosis." (PMID 26415510, 2015). "Recent studies also suggest that NADPH oxidase 4 (NOX4) is essential for TGF-β-induced differentiation of fibroblasts to myofibroblasts in vitro and for bleomycin-induced pulmonary fibrosis in vivo." (PMID 26448760, 2015). "Lung fibroblasts from patients with idiopathic pulmonary fibrosis (IPF) express higher levels of NOX4 mRNA, and NOX4 siRNA has been found to mitigate the fibrotic response in BLM-treated mice." (PMID 24027357, 2013). "Additionally, during the pathological progression of pulmonary fibrosis, TGF-β increases NADPH oxidase-4 (NOX4), inhibits superoxide dismutase (SOD2) expression, enhances ROS production, and promotes myofibroblast differentiation." (PMID 39026235, 2024). "An imbalance between the levels of NOX4 and nuclear factor-erythroid 2-related factor 2 (NRF2) promotes the pathogenesis of lung fibrosis by enhancing cellular senescence in myofibroblasts, resulting in resistance to apoptosis and persistent fibrosis during IPF pathogenesis." (PMID 37077349, 2023). "The expression of Nox4 has been reported to be significantly increased, and the expression of Nrf2, an antioxidant factor that can neutralize Nox4, to be significantly decreased in lung fibroblasts from patients with IPF and bleomycin-induced pulmonary fibrosis mice." (PMID 35563849, 2022). "It was found that BRD4 was involved in pulmonary fibrosis by downregulating signals after growth factor stimulation, driving TGF-β-induced NOX4 expression in human lung fibroblasts, and mediating NF-kappaB-dependent epithelial-mesenchymal transition of airway epithelium." (PMID 33647885, 2021). "The distinguished antifibrotic effects of the Fab'-conjugated dual siRNA-loaded micelles indicated that NOX4 and PTPN13 might play cooperative roles in developing pulmonary fibrosis." (PMID 33537085, 2021). "Furthermore, several studies have demonstrated that TanIIA attenuates silica-induced pulmonary fibrosis in rats via TGF-β1/Smad signalling suppression, Nox4 inhibition and Nrf2/ARE signalling activation." (PMID 35126133, 2021). "Therefore, the TGFβ1/NOX4 and PDGF/ROCK pathways regulate each other in the process of pulmonary fibrosis." (PMID 34135982, 2021). "Supporting a role for JNK in stromal tissues, JNK1 has been shown to promote lung fibrosis in vivo, and to control ROS production through NADPH oxidase 4 (NOX4) thus inducing myofibroblast differentiation and upregulation of alpha-smooth muscle actin (α-SMA) in human breast stromal cells." (PMID 31419957, 2019).
pulmonary fibrosis (continued). "Metformin reduces the expression levels of NOX4, SMAD phosphorylation, and αSMA with concomitant attenuation of lung fibrosis in BLM treatment, suggesting that the anti-fibrotic mechanism of metformin is mainly attributable to inhibition of TGF-β-mediated myofibroblast differentiation." (PMID 27576730, 2016). "Previous studies demonstrated effective attenuation of bleomycin-induced lung fibrosis in rodents by airway delivery of siRNAs targeting IL-13 receptor α2, NADPH oxidase-4 (NOX4), plasminogen activator inhibitor-1 (PAI-1), and the collagen-specific chaperon HSP47." (PMID 26859835, 2016). "Inhibition of ROS production by NOX4 gene deletion and administration of the radical scavenger NAC were shown to have protective effects against alveolar epithelial injury in the bleomycin-induced lung fibrosis model." (PMID 23517551, 2013). "In our study, the expression of NOX4 was significantly increased after 28 days of silica exposure, while the NOX2 expression had no changes in silica-induced rat, which was inconsistent with the results of upregulated NOX2 mRNA expression in silica-induced pulmonary fibrosis." (PMID 38720270, 2024). "An abnormal increase in NOX4, coupled with a lack of Nrf2 activation in senescent myofibroblasts, leads to a persistent redox imbalance that is closely correlated with ROS accumulation and pulmonary fibrosis." (PMID 39251935, 2024). "Nevertheless, our study showed that targeting NOX4-generated ROS and disrupting the self-sustaining cycle between NOX4, ROS, and NLRP3 inflammasomes could effectively inhibit the occurrence and progression of pulmonary fibrosis." (PMID 38166847, 2024). "Prior studies have identified NADPH oxidase 4 (NOX4), mouse double minute 4 homolog (MDM4), and the transcription factor myogenic differentiation 1 (MyoD) as factors that contributed to myofibroblast senescence and apoptosis resistance during persistent lung fibrosis in aged mice." (PMID 35167499, 2022). "However, a recent study demonstrated that Nox4 mediates the profibrotic polarization of lung macrophages, where genetic ablation of Nox4 in macrophages led to decreased ECM deposition and protection from asbestos-induced pulmonary fibrosis." (PMID 32360174, 2020). "Additionally, these inhibitors inhibit the TGF-β-induced increase in NOX4 and ACTA2 and the reduction in SOD2 while increasing Nrf2 activity, thereby reducing the level of ROS in cells and fibroblast activation and promoting the regression of pulmonary fibrosis in mice." (PMID 39215370, 2024). "However, Nox4 is not the only molecule that mediates fibroblast apoptosis in pulmonary fibrosis." (PMID 35111363, 2022). "Importantly, our finding that Brd3 and Brd4, but not Brd2, are involved in NOX4 regulation by TGF-β suggests that a degree of selectivity may be possible when considering BET inhibitors as possible therapeutic agents in pulmonary fibrosis." (PMID 31119153, 2019).
diabetic nephropathy (88 papers, 2013 to 2025). "Increasing evidence has reported that NOX4 plays a crucial role in redox processes associated with various types of renal diseases, including diabetic nephropathy, hypertensive nephropathy, acute kidney injury and renal cell carcinoma." (PMID 41154471, 2025). "According to this, diabetic nephropathy has been associated with the downregulation of FoxO in addition to the activation of NOX4 activity." (PMID 37298303, 2023). "This is associated with elevations in the mitochondrial associated enzyme (NADPH oxidase) Nox4, an important contributor to the development of diabetic nephropathy, also produces hydrogen peroxide." (PMID 31040788, 2019). "Previous studies have suggested that Nox4 expression in the kidney is associated with the development and progression of chronic kidney disease, particularly diabetic nephropathy with renal fibrosis." (PMID 29329317, 2018). "Overexpression of both p22-phox and NOX-4 subunits has been previously associated with diabetic nephropathy." (PMID 30425780, 2018). "Although numerous clinical and experimental studies have linked increased NOX4 expression to the pathogenesis of diabetic retinopathy and diabetic nephropathy, the exact pathophysiological mechanisms remain unclear." (PMID 36829947, 2023). "The NOX4 inhibitor GKT137831 can alleviate podocyte injury caused by diabetic nephropathy." (PMID 37841924, 2023). "Additionally, the development of diabetic nephropathy in rats has been linked to the regulation of NOX4 levels by miR-25, where NOX4 is a catalytic subunit of NADPH oxidase." (PMID 25264560, 2014). "In fact, we and others have shown that increased Nox4-derived ROS in glomerular and tubular compartments were sufficient for renal hypertrophy and albuminuria in rodent models of diabetic kidney disease." (PMID 39761275, 2025). "Currently, the role of NOX4 in the pathogenesis of diabetic nephropathy and related complications has been confirmed." (PMID 41154471, 2025). "The genetic manipulation or pharmacological inhibition of Nox4 effectively alleviates renal protection in the setting of long-term diabetic nephropathy induced by STZ administration in ApoE(−/−) mice." (PMID 38671903, 2024). "The NOX4-derived ROS was involved in the inflammation and the subsequent renal fibrosis process of diabetic nephropathy." (PMID 38195664, 2024). "This emphasizes the importance of NOX4 in podocytes in driving fibrosis progression in models of diabetic nephropathy." (PMID 36658776, 2023). "Growing evidence showed that NOX4 plays a role in the pathogenesis of various kidney diseases, such as diabetic nephropathy 11, hypertensive nephropathy 12, obstructive nephropathy 13, as well as AKI induced by ischemia/reperfusion injury and cisplatin 14-18." (PMID 37284448, 2023). "For instance, one of the more harmful effects occurs in the kidneys, as AMPK inactivation stimulates the NOX4 isoform, and the superoxide burst damages glomerular cells, contributing to diabetic nephropathy." (PMID 37298303, 2023). "AMPK activation can profoundly suppress NADPH oxidase 4- (NOX-4-) mediated fibroblast activation in diabetic nephropathy." (PMID 36818747, 2023). "It stands to reason that STZ-induced diabetic nephropathy as confirmed by changes in urinary albumin protein and glomerular histomorphic alterations which coincided with increased NOX4 and NADPH oxidase activity." (PMID 36670932, 2022). "Renal Nox4 expression is elevated in kidney diseases, including diabetic nephropathy and hypertensive nephropathy, and it contributes to the redox process in various CRF models." (PMID 36144240, 2022). "MALAT1 aggravates renal tubular epithelial injury by interacting with LIN28A to activating the Nox4/AMPK/mTOR signaling in rats with diabetic nephropathy." (PMID 35813614, 2022).
diabetic nephropathy (continued). "Previous publications have revealed that NOX4 overexpression exacerbated tubular damages in diabetic nephropathy, ischemia/reperfusion- or cisplatin-induced AKI, obstructive nephropathy, and hypertensive nephropathy." (PMID 36611810, 2022). "MALAT1, LIN28A and Nox4 are upregulated in diabetic nephropathy tissues and high glucose-treated HK-2 cells." (PMID 35813614, 2022). "To note, that our group and others previously showed a link between AMPK signaling pathway and NOX4 in diabetic nephropathy." (PMID 34680477, 2021). "GKT137831 is in spite this going through phase 2 clinical trials in diabetic nephropathy targeting NOX1/NOX4 activity." (PMID 34099836, 2021). "NOX4 was also found to be targeted by miR-146a in diabetic nephropathy, while overexpression of miR-146a was accompanied by amelioration of both inflammation and OxS." (PMID 32962281, 2020). "Very recently, Nox4 was identified as one of critical HuR targets, particularly in diabetic nephropathy." (PMID 32478392, 2020). "This is in accordance with previous findings that NOX4 reverses the protective effect of miR-423-5p in diabetic kidney diseases." (PMID 32552665, 2020). "By stimulating several signaling pathways, Nox4 leads to redox processes including diabetic nephropathy, acute kidney injury, obstructive nephropathy, hypertensive nephropathy, carcinoma of the renal cells and other renal diseases." (PMID 33180794, 2020). "This is likely due to the protective nature of Nox4 in the macro-vasculature contrasted by its pathological action in the diabetic kidney disease." (PMID 33396868, 2020). "This is a novel finding suggesting that increased PRR contributes to enhanced mitochondria NOX4 expression and activity in diabetic kidney disease." (PMID 31406124, 2019). "Among them, Nox4 is the predominant form in the kidney and has been implicated in the production of ROS in the kidneys in both basal and pathologic conditions such as diabetic nephropathy and chronic kidney disease; upregulation of Nox4 may be important in renal oxidative stress and kidney injury." (PMID 29329317, 2018). "NADPH oxidase 4 (NOX4) plays a major role in renal oxidative stress of diabetic kidney disease (DKD)." (PMID 29854821, 2018). "NOX4, which is ubiquitously expressed but shows particularly high expression in the kidney, was proposed to be a major source of ROS in diabetic nephropathy." (PMID 28326327, 2017). "NOX4 expression appears to increase largely during diabetic nephropathy in podocytes and mesangial cells." (PMID 27924932, 2016). "PL has been demonstrated to downregulate Wnt signaling in human colorectal cancer cells and interrupt the pathways of NOX4 signaling in tubulointerstitial fibrosis present in diabetic nephropathy." (PMID 26550019, 2015). "In rat models of streptozotocin-induced diabetic nephropathy, the expression of p47phox, p22phox, and NOX4 was found upregulated in glomeruli." (PMID 24319690, 2013). "Mechanistically, superoxide production in the intrarenal artery and NOX4 member of NADPH oxidase in the renal cortex that contribute to diabetic nephropathy were also prevented by the Rho kinase inhibitor." (PMID 24129169, 2013). "NADPH oxidase 4 (Nox4) is reported to be the major source of reactive oxygen species (ROS) in the kidneys during the early stages of diabetic nephropathy." (PMID 23991195, 2013). "This study demonstrates that plumbagin ameliorates the development of diabetic nephropathy through pathways that include Nox4 signalling." (PMID 23991195, 2013). "The aim of this study was to investigate the role of Nox4 inhibition on TGFβ1-induced fibrotic responses in proximal tubular cells and in a mouse model of diabetic nephropathy." (PMID 23991195, 2013). "Blunting NOX4 upregulation may alleviate diabetic nephropathy, partially by inhibiting ERS and inflammatory responses, thereby mitigating renal parenchymal damage." (PMID 41154471, 2025).
diabetic nephropathy (continued). "Moreover, ChIP assays revealed that EGR1 was a transcriptional activator of NADPH oxidase 4, a key oxidative stress enzyme in diabetic kidney disease." (PMID 38166990, 2024). "Resveratrol treatment was found to reduce the expression of inflammatory factors NF‐κB, p65, receptor for advanced glycation end products (RAGE), and NADPH oxidase 4 (NOX4) in a mouse diabetic nephropathy model, suggesting its potential role in mitigating chronic inflammation." (PMID 38685568, 2024). "The role of magnesium sulfate (MgSO4) administration to prevent diabetic nephropathy (DN) by reducing insulin resistance (IR) and the relationship of this action with gender and the expression of NOX4 and ICAM1 genes in the parents and their offspring were studied." (PMID 36755074, 2023). "Interestingly, NOX4 deletion or inhibition in a mouse model of diabetic nephropathy or NOX4 silencing in human podocytes markedly suppressed oxidative stress, inflammation, profibrotic factor expression, and enhanced podocyte marker expression." (PMID 36818747, 2023). "Inhibition or deletion of NOX4 has been shown to slow the progression of diabetic kidney disease." (PMID 37047807, 2023). "Furthermore, it has been reported that the upregulation of NAD(P)H oxidase 4 (NOX4) plays an important role in causing renal oxidative stress and kidney injury in animal models of chronic kidney disease (CKD) and diabetic nephropathy (DN)." (PMID 36499723, 2022). "As Nox4/AMPK/mTOR signaling has been reported to be implicated in diabetic kidney disease, we hypothesized that the AMPK/mTOR signaling might be implicated in Nox4-mediated regulation of HG-induced injury." (PMID 35813614, 2022). "Intriguingly, among 5 miRs identified with a precise and contiguous 7 nucleotide alignment match with the 3′-UTR of NOX4 mRNA, only miR-25 was decreased in the renal cortex of rats with diabetic nephropathy presentation and in vitro high glucose treatment of mesangial cells." (PMID 36670932, 2022). "Similarly, a detrimental effect of NOX4 activation and a renoprotective effect of NOX4 clearance have been shown in renal ischemia/reperfusion injury and diabetic nephropathy." (PMID 35528519, 2022). "We speculated that ADMA induced NOX-4 derived ROS generation could be involved in the early events of diabetic kidney disease such as the extracellular matrix accumulation." (PMID 32994511, 2020). "NOX4 is upregulated in both diabetic nephropathy and obesity-related CKD." (PMID 33121167, 2020). "The capacity of RLE to prevent renal damage during the progression of the nephropathy through its capacity to inhibit NOX4 increase, might represent a novel approach to the treatment of diabetic nephropathy." (PMID 32466228, 2020). "Further, patients with diabetic nephropathy were characterized by decline in miR-423-5p, and detailed studies elucidated that HG-elicited injury of podocytes was also attributed to upregulation of direct target of miR-423-5p, NOX4." (PMID 32962281, 2020). "However, in contrast to complications, such as diabetic nephropathy, Nox4 has been demonstrated to be atheroprotective." (PMID 33396868, 2020). "Interestingly, the role of ADAM17 as an upstream regulator of Nox4 was recently reported to be involved in extracellular matrix accumulation during diabetic nephropathy." (PMID 32024241, 2020). "Therefore, many studies have demonstrated AMPK dependent NOX4 downregulation in the diabetic kidney, suggesting a protective role of NOX4 in diabetic nephropathy." (PMID 33121167, 2020). "In a similar context, the observation that microRNA miR-25 may contribute to the negative regulation of Nox4 has been reported in diabetic nephropathy." (PMID 27895046, 2017). "Therefore many previous studies focused on the role of NOX4 in renal physiology and pathophysiology leading to the conclusion that NOX4 is a major source of ROS in diabetic nephropathy." (PMID 28099519, 2017).